HOXC-AS1 (HOXC cluster antisense RNA 1)
Gene: Long non-coding RNA gene on chromosome 12 (53,999,016 to 54,000,011, reverse strand). Ensembl gene ENSG00000250451.
Diseases named in the same sentence as HOXC-AS1 in open-access papers:
HOXC-AS1 is named in the same sentence as 11 diseases in open-access papers, as found by Europe PMC text mining. Sharing a sentence is not in itself a finding about the gene and the disease. The quoted sentences say what the papers report.
gastric cancer (4 papers, 2022 to 2025). A primary or metastatic malignant neoplasm involving the stomach. "HOXC‐AS1 promotes gastric cancer growth and metastasis in vivo and in vitro, and its silence hinders the growth of castration‐resistant prostate cancer." (PMID 37850692, 2024). "HOXC‐AS1 is a novel lncRNA which has already been discovered to play an oncogenic role in gastric cancer and nasopharyngeal carcinoma." (PMID 36510377, 2023). "Long non‐coding RNA HOXC cluster antisense RNA 1 (HOXC‐AS1) is a novel lncRNA whose cancer‐promoting effect in gastric cancer and nasopharyngeal carcinoma has already been demonstrated." (PMID 36510377, 2023). "Long non‐coding RNA HOXC‐AS1 has already been elucidated to be overexpressed in gastric cancer and nasopharyngeal carcinoma." (PMID 36510377, 2023). "The lncRNA HOXC cluster antisense RNA 1 (HOXC-AS1) is involved in several types of cancer, such as gastric cancer and nasopharyngeal carcinoma (NPC)." (PMID 40801625, 2025). "Overexpression of HOXC-AS1 would accordingly sponge greater quantities of miR-99a-3p, leading to the upregulation of MMP8, eventually facilitating the progress of gastric cancer." (PMID 35884594, 2022). "Long noncoding RNAs, including the HOXC Cluster Antisense RNA 1 (HOXC-AS1), are reported to be critical during the occurrence and progression of gastric cancer." (PMID 35884594, 2022).
nasopharyngeal carcinoma (3 papers, 2022 to 2025). A carcinoma arising from the nasopharyngeal epithelium. "LncRNA HOXC cluster antisense RNA 1 (HOXC-AS1) was reported to sponge miR-4651 and increase expression of FOXO6, promoting advancement of nasopharyngeal carcinoma." (PMID 35884594, 2022).
carotid atherosclerosis (1 paper, 2021). A thickening and loss of elasticity of the walls of carotid arteries that occur with formation of atherosclerotic plaques. "HOXC cluster antisense RNA 1 (HOXC‐AS1) and homeobox C6 (HOXC6) were shown to be downregulated in carotid atherosclerosis via microarray analysis." (PMID 33340430, 2021).
esophageal carcinoma (1 paper, 2023). A primary or metastatic malignant neoplasm involving the esophagus. "Since HOXC‐AS1 functioned in SIRT1 mRNA stability, we investigated whether HOXC‐AS1 was involved in the development of esophageal carcinoma via SIRT1." (PMID 36510377, 2023).
esophageal squamous cell carcinoma (1 paper, 2023). Esophageal squamous cell carcinoma (ESCC) is a type of esophageal carcinoma (EC) that can affect any part of the esophagus, but is usually located in the upper or middle third. "HOXC‐AS1 was significantly overexpressed in esophageal squamous cell carcinoma cell lines KYSE30 and Eca109 than that in human normal esophageal epithelial cells (HEEC)." (PMID 36510377, 2023).
Hypertension (1 paper, 2023). The presence of chronic increased pressure in the systemic arterial system. "Multiple HOXC genes: HOXC-AS1-3, HOXC4, HOXC5, HOCX6, HOXC8, HOXC9 and HOXC10 were also shared between subsets of GORD, hypertension and precordial pain." (PMID 37410157, 2023).
Oral leukoplakia (1 paper, 2025). A thickened white patch on the oral mucosa that cannot be rubbed off. "In conclusion, we showed that HOXC9 knockdown can restore the CSCs and migration abilities of DOK cells overexpressing HOXC-AS1, thereby suggesting that HOXC-AS1 interacts with HOXC9 to increase tumor stemness of oral leukoplakia and promote malignant transformation of oral leukoplakia." (PMID 39895798, 2025).
cancer (4 papers, 2019 to 2025). A tumor composed of atypical neoplastic, often pleomorphic cells that invade other tissues. "LncRNA HOXC‐AS1 plays a cancer‐promoting role in a variety of tumors, but its functions in ESCC still remain unknow." (PMID 36510377, 2023). "Some of the irlncRNAs previously associated with the malignant phenotypes of various cancers, including MIAT, TYMSOS, LINC01063, HOXC-AS1, LINC02454, SCAT1, and LINC01322 were identified in the process of modeling in this study." (PMID 34167440, 2021). "As predicted by three online tools including UCSC, JASPAR and PROMO, HOXC-AS1 seemed to be regulated by c-MYC, a well-recognized oncogene in diverse cancers including GC." (PMID 31870402, 2019). "HOXC cluster antisense RNA 1 (HOXC-AS1) is a novel lncRNA which has never been investigated in cancer." (PMID 31870402, 2019). "In summary, the present research elucidated a HOXC-AS1-MYC feed-forward loop in exacerbating tumor growth and metastasis in GC, which offers the first evidence for HOXC-AS1 as a tumorigenic lncRNA in cancer and could also highlight HOXC-AS1 as a promising target for GC treatment." (PMID 31870402, 2019).
tumor (3 papers, 2019 to 2025). "We next performed rescue experiments, which revealed the partial reversal of the inhibitory effects of HOXC-AS1 on tumor sphere formation and EMT in HOXC9 OE DOK cells." (PMID 39895798, 2025). "The tumor size, weight and volume were significantly lower after HOXC‐AS1 knockdown." (PMID 36510377, 2023). "Because both IGF2BP2 and SIRT1 play an important role in tumor, we hypothesize that their mutual regulation also can affect the occurrence and development of ESCC, lncRNA HOXC‐AS1 acts as a molecular scaffold in this progress." (PMID 36510377, 2023).
HOXC-AS1 also shares sentences with these, for which no sentence is quoted: oral squamous cell carcinoma (1 paper); prostate carcinoma (1).